IFITM3 (interferon induced transmembrane protein 3)
Diseases named in the same sentence as IFITM3 in open-access papers (continued):
Sharing a sentence is not in itself a finding about the gene and the disease.
viral infection (continued). "These included IFITM2 and IFITM3, IFIT family members which play a role in viral infection and SPOCK2, upregulated upon virus infection and recognized as protective against influenza infection." (PMID 39026668, 2024). "We thus investigated the expression of four ISGs acting on different steps of viral infection (i.e., OAS1, IFITM3, ISG15, MxA) in lysates of HAEs infected with A/H3N2, A/H1N1, D614G and Omicron viruses in single and coinfections." (PMID 39038029, 2024). "For example, the interferon-induced transmembrane protein 3 (IFITM3) induces accumulation of cholesterol in cellular vesicles to restrict PRRSV membrane fusion and prevent viral infection." (PMID 39413144, 2024). "Cluster 3 (FCGR3A+) was enriched for IFITM3 and FCGR3A, related to the interferon response, inhibition of viral replication and ability to kill target cells after viral infection." (PMID 37078407, 2023). "Well characterized immune regulators, like Clec4e, H2q6 and Ifitm3, have defined roles in LACV or other viral infections." (PMID 37202395, 2023). "While it is established that murine IFITM3 restricts SARS-CoV-2 infection and limits viral disease in vivo, the roles played by human IFITM proteins during SARS-CoV-2 infection have remained controversial." (PMID 37425811, 2023). "It has been reported that interferon can significantly trigger the production of many interferon-induced genes (IFIT1, IFITM3, MX-1, OASL, ISG15, PKR, GBP1, Viperin, BST2, IRF-1, and CXCL10), which play key roles in the resistance to viral infection." (PMID 36337195, 2022). "Moreover, the minor allele of rs34481144 is also associated with enhanced methylation on the IFITM3 promoter of CD8+ T cells, and general transcriptional repression of the broader locus surrounding IFITM3, which includes several genes known to be involved in host responses to viral infection." (PMID 33240681, 2020). "IFITM3 was constitutively expressed in mouse lung-resident memory CD8+ T cells after challenge with influenza virus, enabling the mice to withstand viral infection during a secondary challenge and effecting quick protection at the site of viral entry." (PMID 32321380, 2020). "Interferon-induced transmembrane protein 3 (IFITM3), an INF-stimulated effector protein, plays important roles in restricting virus infection in host cells." (PMID 33195285, 2020). "Interferon-induced transmembrane protein three (IFITM3) is a proinflammatory cytokine belonging to the group of interferon (IFN) stimulated genes (ISGs), which are induced after viral infection." (PMID 32754450, 2020). "The top-scoring genes in the network include the members of Interferon Induced Transmembrane Proteins (IFITM1 and IFITM3) followed by MT1E, MT1X, and MT1G and OASL, all essential proteins involved in the innate immune response to viral infection." (PMID 32012164, 2020). "In viral infections, such as the dengue virus or influenza A virus, IFITM1 at the cell surface or in the early endosomal pathway suppresses virus entry, whereas IFITM3 prevents virus entry in the late endosomal pathway." (PMID 30704088, 2019). "The expression of IFITM3 in Vero cells strongly suppressed the cytopathic effect (CPE) and plaque formation of sequential rounds of virus infection." (PMID 29503647, 2018). "In this work, we applied the HiPPIP model to discover novel PPIs of IFITM1 and IFITM3, to potentially accelerate the discovery of the mechanism by which they inhibit ZIKV and other viral infections." (PMID 29333229, 2016). "In addition, some studies show that IFITM3 is also important in the mediation of other virus infections such as West Nile Virus and Dengue Virus and this hypothesis could justify the higher percentage of C allele carriers in the ILI hospitalized Influenza negative cases." (PMID 27351739, 2016).
viral infection (continued). "By maintaining expression of IFITM3, IAV-specific tissue resident memory T cells contained in the lung mucosa can withstand viral infection during a secondary challenge and effect quick protection at the site of viral entry." (PMID 26600246, 2015). "Overexpression of IFITM3 and other ISGs, such as IFN-induced guanylate-binding protein 1 (GBP1) and stimulator of IFN genes (STING), has been reported to induce autophagy during virus infection." (PMID 40681213, 2025). "To further investigate whether the endogenous IFITM3 induced by IFNs facilitates PEDV infection, we assessed the impact of IFN-β on viral infection in Huh7.5 cells." (PMID 40353666, 2025). "We then evaluated the expression of four interferon-stimulated genes (ISGs) acting on different steps of viral infection (i.e., OAS1, IFITM3, ISG15, and MxA) in lysates of nasal HAEs infected with each single virus or coinfected with the two viruses simultaneously or sequentially 1 or 4 days apart." (PMID 40366152, 2025). "Along with its role in the viral cell entry, the TMPRSS2 activity also influences the Interferon-induced transmembrane protein 3 (IFITM3), which has an important role in the control of SARS-CoV-2 infection given its role in other viral diseases along with its interaction with the S protein." (PMID 37426824, 2023). "To identify novel functional partners of IFITM3, we took advantage of the fact that, in the absence of viral infection, this protein can be incorporated into exosomal vesicles." (PMID 37896772, 2023). "IFITM3 produces an immune effector protein that promotes mucosal immune cell durability by increasing CD8+CTL number in the airways, which is vital in immunity against viral diseases." (PMID 36743382, 2023). "IFITM3 exhibits antiviral action against IAV, SARS coronavirus, and numerous other viruses and has emerged as a crucial innate immunological barrier against viral infections in vertebrates." (PMID 37323564, 2023). "Overexpression of IFITM1, IFITM2, and IFITM3 proteins did not restrict the entry of pseudoparticles carrying arenavirus envelope glycoproteins and live virus infection." (PMID 35283811, 2022). "However, during viral infection, the expression of ISGs including DHX58, IFITM3, ISG15, and OASL was upregulated in the livers of WT mice, while Neurl3−/− livers expressed a higher level of proteins related to inflammatory response such as S100A9 and CD47." (PMID 35792897, 2022). "In a previous EPF genome-wide expression study (GWES), several genes involved in the early stages of viral infection were overexpressed in patients with the generalized form of EPF compared to healthy individuals, including IFITM3, APOBEC3A, APOBEC3G, OAS1, OASL, SERINC3, and RPLP2." (PMID 35632621, 2022). "This includes the upregulation of classical antiviral genes such as IFITM3, even in the absence of viral infections." (PMID 36194487, 2022). "At the gene level, we found that NF could significantly induce a set of ISG expressions, such as MCL1, IFITM3, B2M, BST2, OAS1, and PKR to function against virus infection." (PMID 35910807, 2022). "Meanwhile, we found that IFNs could significantly trigger the production of a variety of IFN-induced genes (IFIT1, IFITM3, Mx-1, OASL, ISG15, PKR, GBP1, Viperin, BST2, IRF-1, and CXCL10) and MHC molecules, which play key roles in resistance to virus infection." (PMID 32655518, 2020). "Surprisingly, silencing of endogenous IFITM3 did not exert any significant effect on virus infection, but it regulated the antiviral activity of type Ι IFN and modulated the vaccinia virus-induced cell death." (PMID 29503647, 2018). "Duck IFITM3 also mediates restriction of H1N1, H6N2 and H11N9 virus infections." (PMID 29104227, 2017). "Ifitm3 has been reported to be upregulated in spleen during VEEV-TrD infection in macaques and has been shown to play a critical role in protection against several viral infections." (PMID 28446152, 2017).
viral infection (continued). "Over-expressing IFITM1 significantly enhanced KSHV infection of cells; IFITM3 moderately enhanced KSHV infection while IFITM2 did not alter the viral infection." (PMID 29269892, 2017). "Finally, we found that genes closest to sites with significant negative coefficients for age included IFITM1, IFITM2, and IFITM3, which are interferon response genes that are activated following viral infections, such as the hepatitis C virus." (PMID 39637179, 2024). "Additionally, LSD1 activates IFITM3 via demethylation, leading endocytosed HCV virions to degradation and infection to failure, rendering LSD1 a crucial component of IFN-induced immune response against HCV viral infection." (PMID 37947646, 2023). "IFITM3 is a key mediator of the early innate cellular response, however it functions to inhibit phagocytosis, which is beneficial in viral infections, but not with intracellular bacterial pathogens like Listeria which have evolved strategies to exploit its function to avoid phagocyte killing." (PMID 35720382, 2022). "Additionally, the Ifitm3 gene promoter, which regulates the expression of interferon-induced transmembrane protein 3 (IFITM3), that confers broad resistance to viral infection, was selectively unmethylated in memory CD8 T cells in the lung during influenza infection in mice." (PMID 34831166, 2021). "However, in the absence of IFNα2b, knockdown of endogenous IFITM3 had no impact on virus infection in both HeLa and 293T cells (black bars)." (PMID 29503647, 2018). "With the recent recognition of IFITM3-mediated restriction of nonenveloped reoviruses, the pleotropic effect of IFITM3 on diverse virus infections, or the co-operative role of all antiviral IFITM proteins as a layered defense to different virus infections, remains to be determined." (PMID 24278312, 2013). "Thus, the importance of PPARγ, APOBEC3G and IFITM3 upon viral infection could not be denied due to their involvement in pathways affecting viral pathogenicity, specifically in viral replication." (PMID 38263024, 2024). "However, more recent work has suggested that IFITM3 may enhance SARS-CoV-2 fusion at the plasma membrane, with clear distinctions drawn between enhancement of viral infection at the plasma membrane and amphipathicity-based mechanisms used for endosomal SARS-CoV-2 entry restriction." (PMID 36009555, 2022). "Thus, IFITM3 is necessary for the innate immune restriction of influenza virus in mice and humans, and further understanding its biochemical properties may inspire new strategies for preventing or treating influenza and other IFITM-sensitive virus infections." (PMID 26075508, 2015). "However, the ability of IFITM3 to inhibit virus infections was not demonstrated until 2009 when researchers performing a genome-wide siRNA screen for influenza virus host dependency factors conversely discovered that IFITM3 knock-down resulted in increased influenza virus infection of cells." (PMID 30662816, 2018). "Given the negative impact of MARCH8 on the level of IFITM3, we suspected that MARCH8 KO may render cells more resistant to virus infection." (PMID 41197719, 2025). "Although IFITM3, an ISG localizing to late endosomes, can limit many viral infections, whether or not it restricts the infection of RV is still unknown." (PMID 36366505, 2022). "The rs12252-C mutant protein IFITM3 ND21 was not flexible enough to effectively prevent the fusion of the virus with the endocytic membrane, which in turn reduced the ability of the immune system to defend against viral infection." (PMID 36325336, 2022).
influenza (104 papers, 2012 to 2025). An acute viral infection of the respiratory tract, occurring in isolated cases, in epidemics, or in pandemics; it is caused by serologically different strains of viruses (influenzaviruses) designated A, B, and C, has a 3-day incubation period, and usually lasts for 3 to 10 days. "Numerous studies have shown the relationship between IFITM3 SNPs and severe influenza, but several fail to show consistent associations with severe outcomes (37, 38, 41, 42, 51, 57, –, 64)." (PMID 40237465, 2025). "We posit that adaptive immune mechanisms, including pre-existing antibodies and memory T cells against seasonally circulating viruses, compensate for IFITM3 deficiencies, therefore masking its role in seasonal influenza." (PMID 40237465, 2025). "Within the human population, there are two single nucleotide polymorphisms (SNPs) in the IFITM3 gene that have been credibly associated with increased severity of influenza." (PMID 40237465, 2025). "Given the broadly enhanced susceptibility of IFITM3 KOs to influenza viruses, our results suggest that these mice are potentially useful as a pre-clinical influenza vaccine testing model." (PMID 40501891, 2025). "IFITM3 variants are associated with severe disease in influenza infection and an Ifitm3 knockout mouse is susceptible to low pathogenicity infections." (PMID 38421405, 2024). "Recent studies of single nucleotide polymorphisms (SNPs) in the interferon-induced transmembrane protein 3 (IFITM3) gene demonstrate the potential impact of such variants in the susceptibility to severe influenza infection." (PMID 38275224, 2024). "Human IFITM3 deficiencies are associated with heightened severity of influenza, and data are emerging that IFITM3 deficiencies are a risk factor for severe COVID-1916–20." (PMID 39477971, 2024). "The IFITM3 gene encodes an interferon-induced membrane protein that facilitates immunity to influenza, an H1N1 virus, the West Nile virus and the dengue virus." (PMID 37138773, 2023). "IFITM1 and IFITM3 are crucial for protection against influenza, and various single nucleotide polymorphisms altering their function have been linked to disease susceptibility." (PMID 35708622, 2022). "Further supporting its relevance in dissecting influenza pathologies, genetic deficiencies in IFITM3 associate with susceptibility to severe disease in humans." (PMID 35544568, 2022). "In particular, the IFITM3 molecule has been shown to be important in response to influenza infection and implicated in increased susceptibility through a single nucleotide polymorphism (SNP) in the IFITM3 gene, rs12252-C." (PMID 36275684, 2022). "On the other hand, IFITM3 was negatively associated with the number of symptoms reported by influenza patients and correlated with increased heart rate (HR) on admission." (PMID 35708622, 2022). "The IFITM3-rs-12252 allele has been associated with severe disease and death with influenza and other viruses." (PMID 34434219, 2021). "Since genetic host factors, such as specific HLA types and IFITM3 SNPs have been associated with influenza disease severity we compared these genetic factors between influenza+ and influenza- patients." (PMID 33976217, 2021). "We did find a significant pooled association for the IFITM3 SNP rs12252-C allele and severity of influenza infection, which is in line with previously published meta-analyses." (PMID 34930124, 2021). "The expression of the rare rs12252-C allele in the IFITM3 gene results in a truncated protein that lacks 21 amino acids at the end of the amine, which reduces its impact on influenza infection control." (PMID 33766078, 2021). "Although the association has not always been clear, a recent meta-analysis including 12 studies and >16 000 subjects confirmed the link between the IFITM3 minority allele and influenza severity." (PMID 34524075, 2021).
influenza (continued). "A recent study found that genetic polymorphism in Interferon-induced transmembrane protein 3 (IFITM3), were associated with the magnitude of the antibody response after seasonal influenza vaccination." (PMID 34372607, 2021). "Individuals with the at-risk IFITM3 rs12252 allele had a 6-fold risk of severe influenza and were associated with early hypercytokinemia (cytokine storm) and increased mortality with influenza infection." (PMID 34434219, 2021). "IFITM3 rs12252-C/C were also reported to be associated with severe influenza, presumably due to a truncated IFITM3 protein with reduced antiviral potency, although others found no such association." (PMID 34372607, 2021). "Another important polymorphism in the IFITM3 gene associated with severe influenza is located in the 5′ UTR and leads to transcriptional repression through increased CTCF binding to the promoter." (PMID 34524075, 2021). "Many alleles have been correlated with an increase in the severity of influenza, but the most studied allele is the G variant of the SNP rs12252 of the IFITM3 (IFITM3 rs12252)." (PMID 34434219, 2021). "That was the first study to evaluate the association of IFITM3 rs12252 polymorphism with susceptibility to mild influenza with regards to diabetes, hypercholesterolemia and BMI in an Iranian population." (PMID 33766078, 2021). "Research has shown that deleting the first amino-terminal 21-amino-acid or mutating 20-YEML-23 result in relocation of IFITM3 from the endosomal compartments to the plasma membrane, thus losing influenza-inhibitory action." (PMID 32321380, 2020). "This SNP, together with rs34481144, are the two most studied polymorphisms of IFITM3 and have been associated in the past with increased severity in Influenza, Dengue, Ebola, and HIV viruses." (PMID 33240681, 2020). "CD8+ TRM that lack IFITM3 expression exhibit increased susceptibility to influenza infection compared to IFITM3+ CD8+ TRM, and are selectively lost following virus challenge." (PMID 33815352, 2020). "The SNP rs12252-C/C in the interferon-induced transmembrane protein 3-encoding gene IFITM3 that is linked to severe influenza was detected in a patient from Wuhan, China, with mild-to-moderate COVID-19 that required hospitalization but recovered." (PMID 33092637, 2020). "This notion has recently been reinforced by the finding that a polymorphism in the huIFITM3 promoter that reduces IFITM3 expression increases the risk for severe influenza." (PMID 31682595, 2019). "Another important SNP (rs34481144) associated with risk of severe influenza in humans from the United States (US) infected with seasonal IAVs is located in the 5′-UTR of the IFITM3 gene." (PMID 31574965, 2019). "One of the clearest associations of SNPs in genes affecting influenza severity is located in the ISG IFITM3." (PMID 31574965, 2019). "As the best characterized host restriction factor against influenza viruses in vitro and in mouse studies, the importance of IFITM3 aroused the interest to explore its genetic association with severe influenza in humans." (PMID 30498026, 2019). "rs34481144 located at the IFITM3 promoter is associated with severe influenza in three human cohorts." (PMID 30687247, 2018). "A recent study found that another IFITM3 SNP rs34481144 has a strong association with disease severity in three influenza cohorts." (PMID 30687247, 2018). "To control for the effect of residual population admixture on our results, we adjusted genetic association between IFITM3-SNP rs12252 and susceptibility to mild flu for participants’ residence area." (PMID 29121968, 2017). "A single nucleic variation within IFITM3 has been shown to be associated with sever influenza outcome." (PMID 28713779, 2017). "As one of the most important findings in this study, the association between IFITM3 rs12252-C variant and the severe influenza infection is observed." (PMID 28713779, 2017).